SPP1 (secreted phosphoprotein 1)
Description:
Major non-collagenous bone protein that binds tightly to hydroxyapatite. Appears to form an integral part of the mineralized matrix. Probably important to cell-matrix interaction. Acts as a cytokine involved in enhancing production of interferon-gamma and interleukin-12 and reducing production of interleukin-10 and is essential in the pathway that leads to type I immunity.
Synonyms: BNSP; OPN; BSPI; ETA-1; lnc-PKD2-2-3
Tractability: Antibody: a drug acting on it is in phase 2 or 3 trials; UniProt places it where antibodies can reach, with high confidence; its Gene Ontology location is reachable by antibodies, with high confidence; UniProt predicts a signal peptide or a membrane-spanning region.
Target class: Secreted protein
Gene: Protein-coding gene on chromosome 4 (87,975,667 to 87,983,532, forward strand). Ensembl gene ENSG00000118785.
Subcellular location: Secreted
Subcellular location (Human Protein Atlas): Golgi apparatus; Predicted to be secreted
Pathways (Reactome):
Extracellular matrix organization: Degradation of the extracellular matrix; Integrin cell surface interactions
Metabolism of proteins: Post-translational protein phosphorylation; Regulation of Insulin-like Growth Factor (IGF) transport and uptake by Insulin-like Growth Factor Binding Proteins (IGFBPs)
Cellular responses to stimuli: Mechanical load activates signaling by PIEZO1 and integrins in osteocytes
Gene expression (Transcription): RUNX3 Regulates Immune Response and Cell Migration
Signal Transduction: Signaling by PDGF
Gene Ontology:
Molecular function: calcium ion binding; integrin binding; protein binding; small molecule binding; extracellular matrix binding
Biological process: androgen catabolic process; cell adhesion; cellular response to testosterone stimulus; positive regulation of DNA-templated transcription; positive regulation of estradiol secretion; response to vitamin D; bone mineralization; decidualization; embryo implantation; calcium ion homeostasis; cell differentiation; negative regulation of collateral sprouting of intact axon in response to injury; ossification; osteoblast differentiation; positive regulation of bone resorption; response to 2,3,7,8-tetrachlorodibenzodioxine; response to macrophage colony-stimulating factor; response to steroid hormone
Cellular component: extracellular exosome; extracellular region; Golgi apparatus; endoplasmic reticulum lumen; apical part of cell; cytoplasm; perinuclear region of cytoplasm; vesicle
Genetic constraint (gnomAD): Loss-of-function variants: 21 observed, 22.65 expected, observed/expected ratio (o/e) 0.93, 90% interval 0.66 to 1.34. The upper end of that interval is the gene's LOEUF score, 1.34, which puts it in group 5 of 6, group 1 being the genes least tolerant of losing a copy. Missense variants: 363 observed, 409.12 expected, observed/expected ratio (o/e) 0.89, 90% interval 0.81 to 0.97. Synonymous variants: 146 observed, 149.99 expected, observed/expected ratio (o/e) 0.97, 90% interval 0.85 to 1.12.
Homologues: Orthologues: chimpanzee SPP1 (98% identical), macaque SPP1 (93% identical), pig SPP1 (69% identical), rabbit SPP1 (68% identical), rat Spp1 (65% identical), dog SPP1 (64% identical), mouse Spp1 (63% identical), guinea pig SPP1 (55% identical).
Diseases named in the same sentence as SPP1 in open-access papers:
SPP1 is named in the same sentence as 759 diseases in open-access papers, as found by Europe PMC text mining. Sharing a sentence is not in itself a finding about the gene and the disease. The quoted sentences say what the papers report.
breast cancer (294 papers, 2004 to 2026). A primary or metastatic malignant neoplasm involving the breast. "A previous TCGA cohort study showed that SPP1 is significantly increased in breast cancer and associated with poor prognosis." (PMID 41056019, 2026). "Liang reported that individuals with the CC genotype and the C allele of the SPP1 gene at rs11730582 demonstrated a reduced risk of developing breast cancer." (PMID 40428307, 2025). "SPP1‐expressing macrophages have been associated with the M2‐like phenotype in the context of breast cancer, which has been implicated in promoting cancer cell metastasis and growth." (PMID 40056038, 2025). "If approved, the effect would be further exploited to treat diseases where the expression of SPP1 is deficient, such as ectopic calcification in blood vessels, the heart, and kidneys or microcalcification in early-stage breast cancer." (PMID 38920651, 2024). "Single-cell analysis in breast cancer has revealed that SPP1-positive tumor-associated macrophages (TAMs) display significantly increased expression of markers like apolipoprotein E (APOE), CD204, CD68, and CADM1." (PMID 39727934, 2024). "In our study, analysis of scRNA‐seq data from both susceptible and resistant groups of breast cancer chemotherapy revealed an abnormally active signal, SPP1, secreted by macrophages." (PMID 38982317, 2024). "SPP1 overexpression has been implicated in mammary cancer development, and our study corroborates these findings by showing enhanced SPP1 protein levels in both serum and mammary ductal epithelial cells of GCRsim-exposed mice." (PMID 39682141, 2024). "The investigators revealed a strong staining intensity of nuclear SPP1-c which was significantly associated with poor outcomes in patients with early breast cancer." (PMID 38067407, 2023). "In another study, SPP1-associated macrophages in the tumor-adipose microenvironment facilitate breast cancer progression." (PMID 36497286, 2022). "Recently, SPP1 has been implicated as a prognostic and diagnostic marker for certain cancer types, such as gastric cancer, liver cancer, and breast cancer." (PMID 35593388, 2022). "Overexpression of SPP1 is linked to worse prognosis in many cancers, including hepatocellular carcinoma, colorectal cancer, lung cancer, breast cancer, bladder cancer, and acute myeloid leukemia." (PMID 35790930, 2022). "Liang found that people carrying the CC genotype and C allele of the rs11730582 locus of the SPP1 gene had a reduced risk of developing breast cancer." (PMID 36611698, 2022). "It is reported that SPP1 overexpression is associated with high invasive and metastatic potential, poor prognosis, and recurrent disease for cancer patients, such as breast cancer and gastric cancer." (PMID 34367279, 2021). "Higher SPP1 gene expression in primary tumors was found to be associated with risk of recurrence in ER+ breast cancer among patients with endocrine treatment." (PMID 34497807, 2021). "In this case-control study, we demonstrated that high SPP1 gene expression was significantly associated with increased risk of distant recurrence among tamoxifen- treated women with ER+ breast cancer." (PMID 31996744, 2020). "This evidence supports that (i) Spp1 expression is upregulated in breast cancer, (ii) it is linked to metastasis and (iii) its high expression is coupled to poor patient survival." (PMID 31964403, 2020). "The glyco-phosphoprotein osteopontin (OPN), encoded by the SPP1 gene, has previously shown to be associated with poor prognosis in breast cancer." (PMID 31996744, 2020). "The results from mRNA analyses strongly suggest that functional studies are needed in order to find the underlying biological background for SPP1 behaviour in ER+ breast cancer." (PMID 31996744, 2020). "We used a matched case-control design and report that the risk of recurrence for tamoxifen- treated breast cancer patients increases with higher SPP1 expression." (PMID 31996744, 2020).
breast cancer (continued). "SPP1 is a secreted glycoprotein that has been closely associated with the metastasis of various tumors such as gastric cancer, breast cancer, and melanoma." (PMID 31950035, 2019). "This correlation was found to be in the opposite direction in the normal tissue of breast cancer patients, with lower SPP1 expression associated with a low BRCA2 expression haplotype (P-value = 0.038)." (PMID 22513257, 2012). "SPP1 has been associated with breast cancer progression, invasion and metastasis and is present in elevated levels in the blood and plasma of some patients with metastatic cancers." (PMID 21314937, 2011). "Interestingly, SPP1 has been associated with tumor burden and reduced survival in breast cancer patients." (PMID 39682141, 2024). "We then consolidated an OPN pathway and upregulated gene signatures from our findings (Spp1, Timp3, Col11a1, Mmp9, Mmp2, Fn1, Cd44, and Il-4) to interrogate how their predicted activity is associated with relapse-free survival in breast cancer patients." (PMID 39448577, 2024). "Therefore, understanding GCRsim-induced alterations in the signaling axis involving ERα, ERRα, and SPP1 is crucial for elucidating the molecular events associated with GCRsim-induced mammary cancer risk." (PMID 39682141, 2024). "Notably, SPP1 expression in mammary epithelial cells has been implicated in mammary cancer initiation, and elevated plasma levels of SPP1 protein are associated with increased tumor burden." (PMID 39682141, 2024). "In addition, the gene-disease analysis showed that three out of four hub genes (CXCL2, SRC and SPP1) were also associated with mammary neoplasms, pulmonary fibrosis, dermatitis and allergic contact diseases." (PMID 35452485, 2022). "Additionally, the protein-disease interaction networks showed three out of five hub genes (CXCL2, SRC and SPP1) are also associated with mammary neoplasms, pulmonary fibrosis, dermatitis and allergic contact diseases." (PMID 35452485, 2022). "The protein encoded by SPP1, also known as osteopontin, facilitates the combination of mineralized bone matrix and osteoclasts and is overexpressed in a variety of cancers, including breast cancer, lung cancer, pancreatic cancer, and GC." (PMID 32908877, 2020). "Furthermore, analysis of reported expression data on metastatic sub-populations of 4T1 breast cancer revealed that elevated Spp1 expression is associated to lung, bone and liver-specific metastatic activity as well." (PMID 31964403, 2020). "Overall, SPP1 is involved in various stages of breast cancer development, supporting its value as a potential candidate target." (PMID 41056019, 2026). "Coculture with SPP1-knockdown macrophages significantly suppressed the proliferation and migration of breast cancer cells, whereas SPP1 coculture with SPP1-overexpressing macrophages promoted the proliferation and migration of breast cancer cells." (PMID 41056019, 2026). "Functional studies suggest that the reduction of SPP1 inhibits breast cancer cell proliferation and promotes cell apoptosis." (PMID 41056019, 2026). "The effect of macrophages with differential SPP1 expression levels on breast cancer cell proliferation was assessed using CCK-8 and colony formation assays, and their effect on migration was evaluated using Transwell assays." (PMID 41056019, 2026). "Venn analysis of PMRGs and upregulated DEGs revealed two key PMRGs that were upregulated in breast cancer, namely SPP1 and ADM2." (PMID 41056019, 2026). "In clinical samples of breast cancer, we verified the high expression of SPP1 in monocytes–macrophages." (PMID 41056019, 2026). "In the established PMRG set, SPP1 was identified as a preliminary candidate target in breast cancer through various bioinformatics techniques." (PMID 41056019, 2026). "To investigate the impact of SPP1 expression on macrophages in breast cancer cells, we differentiated the THP-1 monocytic cell line into macrophages using PMA induction." (PMID 41056019, 2026).
breast cancer (continued). "As in many other tumour types, breast cancer is characterised by a strong infiltration of macrophages, among which the SPP1+ subset is gaining increasing attention." (PMID 40395129, 2025). "Recent studies have unveiled a striking role for SPP1+ macrophages in HR+ breast cancer, where they establish interactions with tumour‐infiltrating lymphocytes and actively suppress their function." (PMID 40395129, 2025). "Osteopontin is known to be released by THP-1 cells and SPP1 expression is reported in macrophages in breast cancer." (PMID 40017592, 2025). "Conversely, in breast cancer, mast cells recruited and activated by tumor cells can induce transcriptional changes in genes such as SPP1, PDCD1, IL17A, TGFB1, KITLG, and IFNG, leading to anti-tumor effects." (PMID 40495762, 2025). "The high probability of macrophage-derived osteopontin (secreted phosphoprotein 1, SPP1) signaling to various cells exclusively in the younger cohort suggests promotion of breast cancer progression and chemoresistance." (PMID 41188599, 2025). "Previous studies reported that hypoxia induces upregulation of SPP1 expression in both tumor cells and macrophages in breast cancer, and SPP1+ TAMs engage with nearby cells via cellular communication, fostering tumor growth." (PMID 40432877, 2025). "High expression levels of Fib‐11 and CD74 were correlated with improved survival in breast cancer, whereas high SPP1 and CD44 expression predicted worse PDAC outcomes." (PMID 40357856, 2025). "OPN/Spp1 expression emerged as one of the markers in a hypoxic macrophage transcriptome, a predictor of worse outcomes in breast cancer." (PMID 40865052, 2025). "Chemotherapy-induced macrophage phenotype switching has been reported in breast cancer, and our findings suggest that preoperative chemotherapy can significantly reduce SPP1 expression in CRC macrophages, especially in responders." (PMID 40092488, 2025). "These experiments suggest that the co-culture of primary human lung fibroblasts with breast cancer cells leads to a significant and steady increase in gene expression of SPP1, IGF1, POSTN and ACTA2." (PMID 40017592, 2025). "The clinical significance of SPP1 has been further highlighted in recurrent breast cancers, where its levels are markedly elevated, primarily due to macrophages, though endothelial and other stromal cells also contribute." (PMID 40395129, 2025). "Our analysis of human breast cancer samples revealed elevated expression of ERRα and SPP1, mirroring the findings in GCRsim-exposed mammary tissues and suggesting the relevance of these markers in both IR-induced and spontaneous breast cancers." (PMID 39682141, 2024). "Using a human tissue microarray and human breast cancer gene expression analysis, we also highlighted the conserved nature of the ERα-ERRα-SPP1 signaling in human breast cancer development." (PMID 39682141, 2024). "The expression levels of SPP1 mRNA have been identified as potential biomarkers for predicting recurrence in estrogen receptor-positive (ER+) breast cancer patients who have undergone tamoxifen treatment." (PMID 39727934, 2024). "This co-expression of SPP1 and ERRα, particularly in ERα and ERRα-positive breast cancer cells, suggests that upregulation of ERRα is critical for SPP1-positive preneoplastic and neoplastic cells." (PMID 39682141, 2024). "We detected P16Ink4a+ and SPP1+ osteocytes, which preferentially located close to bone marrow areas infiltrated with breast cancer cells." (PMID 38558984, 2024). "Elevated SPP1 levels correlate with adverse breast cancer prognosis, aligning with our prognostic research direction." (PMID 38982317, 2024). "The analysis indicated that Wdr5 is positively correlated with PD-1, PD-L1, and Spp1 expression in both human colon cancer and human breast cancer in myeloid cells, epithelial cells, and T cells." (PMID 39201460, 2024). "In breast cancer, TAM-derived SPP1 has been implicated in promoting cancer cell growth and progression." (PMID 39727934, 2024).
breast cancer (continued). "Breast cancer MDA-MB 231 cells were treated with conditioned medium from SPP1-overexpressed TAM, and tumor stem cell markers (SOX2, CMYC, NANOG, OCT4 gene) and PDL1 genes were detected by RT-qPCR." (PMID 38648200, 2024). "Macrophage-derived osteopontin (secreted phosphoprotein 1, SPP1) signaling to various cells exclusively in the younger cohort is consistent with promotion of breast cancer progression and chemoresistance." (PMID 39483921, 2024). "Studies have shown that knockdown of SPP1 in combination with radiation therapy promotes apoptosis, inhibits the expression of downstream genes, and reduces cell viability in breast cancer cells." (PMID 39545257, 2024). "A meta-analysis revealed the elevation of specific splice variants, namely SPP1-a, SPP1-b, and SPP1-c, in lung cancer and the elevation of SPP1-c in breast cancer as compared to healthy tissue." (PMID 39727934, 2024). "Through cell communication analysis, we identified the SPP1 signal, known to predict breast cancer recurrence post‐tamoxifen treatment." (PMID 38982317, 2024). "A pan-cancer scRNA-seq study on 15 common tumors revealed the presence of SPP1+ TAM in breast cancer, pancreatic cancer, lung cancer, colon cancer, endometrial cancer, nasopharyngeal cancer, ovarian cancer, and thyroid cancer tissues." (PMID 39308672, 2024). "Consistent with our findings, we reveal CEBPB's impact on breast cancer chemoresistance through the SPP1 signalling pathway." (PMID 38982317, 2024). "This indicates that upregulation/activation of both ERα and ERRα is important for SPP1 positive breast cancer cells." (PMID 39682141, 2024). "Previous studies have demonstrated that SPP1 is overexpressed in multiple malignancies and involved in tumorigenesis and metastasis, including colorectal cancer, lung cancer, and breast cancer." (PMID 39557868, 2024). "Aberrant upregulation of SPP1 has been observed in different solid tumors such as lung cancer, glioblastoma, breast cancer, and pancreatic cancer." (PMID 39616302, 2024). "The analysis indicated that the dysregulation of SPP1 is prevalent across various tumor types, including breast cancer (BRCA)." (PMID 39727934, 2024). "Single-cell analysis in breast cancer has also shown that SPP1-positive TAMs express high levels of apolipoprotein E (APOE), CD204, CD68, and CADM1." (PMID 37190178, 2023). "SPP1, encoding by Osteopontin, is an ECM protein which is reported to be overexpressed in a variety of malignancies such as ovarian cancer, breast cancer and CRC." (PMID 37024866, 2023). "Elevated SPP1 expression has been observed in multiple cancers, such as CC colon cancer, lung cancer, prostate cancer, breast cancer, ovarian cancer, multiple myeloma, acute myeloid leukemia, and chronic myeloid leukemia." (PMID 36880057, 2023). "By contrast, several other investigations highlighted that high SPP1 levels were correlated with poor outcomes in many solid malignancies such as prostate cancer, lung cancer, gastric cancer and breast cancer." (PMID 38067407, 2023). "Aberrant over-expression of the SPP1 protein was reported in several solid tumors including prostate cancer, lung cancer, gastric cancer, breast cancer and hepatocellular and it is down-regulated in colorectal and endometrial carcinomas." (PMID 38067407, 2023). "In breast cancer, the level of SPP1 was significantly higher in tumors than in adjacent tissues and was positively correlated with tumor grade and subtype." (PMID 37097499, 2023). "SPP1 is often overexpressed in multiple cancers including pancreatic cancer, lung cancer, gastric cancer, hepatocellular cancer, breast cancer and colon cancer." (PMID 36585688, 2022). "Our results indicated that MMP1, CD24, SDC1, and SPP1 are potential novel prognostic biomarkers and candidate immunotherapy targets for breast cancer." (PMID 35037689, 2022).